PON1 (paraoxonase 1)
Diseases named in the same sentence as PON1 in open-access papers (continued):
Sharing a sentence is not in itself a finding about the gene and the disease.
atherosclerosis (continued). "Accordingly, a low-active paraoxonase allele such as PON1 Q192 should protect against atherosclerosis when compared with the corresponding high-active R192 allele." (PMID 21569287, 2011). "The involvement of PON1 in the pathogenic sequence is further supported by the fact that decreased PON1 activity is associated with an increased prevalence of atherosclerosis and incidence of cardiovascular disease." (PMID 21543280, 2011). "Patients with a mutated PON1 gene show accelerated atherosclerosis as assessed by carotid intima-media thickness (IMT), and two prospective studies associated low PON1 activity with high incidence of major cardiovascular events." (PMID 20604930, 2010). "Taken together, our resultssuggest that the decrease in serum PON1 activity due to lead exposuremay render individuals more susceptible to atherosclerosis, particularlysubjects who are homozygous for the R192 allele." (PMID 16882531, 2006). "PON1 knockout mice are prone to atherosclerosis both induced by diet and apoE deficiency." (PMID 40298833, 2025). "In addition, it is known that the HDL-associated PON1 protein can lower its protective capacity against atherosclerosis when exposed to inflammation." (PMID 39408985, 2024). "PCOS decreases blood PON1 levels, which could be related to a higher risk of heart disease with atherosclerosis." (PMID 38982395, 2024). "Indeed, the activity of the HDL-associated antioxidant PON1 enzyme increased significantly, indicating an improvement in protection against atherosclerosis and cardiovascular diseases due to low- and moderate-intensity aerobic training forms." (PMID 39683642, 2024). "PON1 knockout mice prone to atherosclerosis both induced by diet and apoE deficiency." (PMID 38887979, 2024). "In epidemiological studies EDTA plasma is typically stored, but to test the association between PON1 activity and atherosclerosis when phenyl acetate, paraoxon, diazoxon, or a lactone are employed as substrate, serum is required, because all these activities are highly Ca2+-dependent." (PMID 36873390, 2023). "Furthermore, in experiments to test the contribution of risk factors other than PON1 to atherosclerosis, the atherogenic diet used in, for example rabbits, would have decreased PON1 and contributed to atherogenesis from whatever other cause was being examined." (PMID 36873390, 2023). "PON1 knockout mice fed with a high-fat diet were also more susceptible to develop atherosclerosis." (PMID 36833509, 2023). "The decreased PON1 activity in our study may indirectly indicate that it plays an important role in the pathogenesis of AD due to the risk of atherosclerosis as well as the increase in LDL oxidation." (PMID 37772794, 2023). "We know that reduction in PON-1 level and/or activity is linked to oxidative stress, inflammation, and atherosclerosis, but recent research has shown that it may also be related to mild cognitive impairment." (PMID 37108044, 2023). "While for many years PON-1 has been implicated as a risk factor in atherosclerosis (reviewed), we provide experimental evidence that PON-1 is a major risk factor in CKD progression through regulating renal inflammation and fibrosis in a well characterized model of high-salt induced renal disease." (PMID 35624764, 2022). "Furthermore, PON1 has been implicated in the pathogenesis of several inflammatory diseases, including atherosclerosis, diabetes, and cancer." (PMID 35453382, 2022). "Many studies support the hypothesis that low PON1 activity is associated with increased oxidative stress, risk of atherosclerosis, and cardiovascular disease." (PMID 35889799, 2022). "Low PON1 levels were closely linked to the start and progression of atherosclerosis." (PMID 34702323, 2021). "Hyperhomocysteinemia and hyperthiolactoneemia caused by the imbalance of PON1 activity might be another risk factor for atherosclerosis." (PMID 33628379, 2021).
atherosclerosis (continued). "Likewise, in patients with established atherosclerosis risk factors, an association between PON1 genotype and early forms of atherosclerosis of carotid arteries were examined." (PMID 33670025, 2021). "The connection between oxidative stress and dyslipidemia established by PON1 as an intermediary suggested that it might be involved in the onset of acute ischemic stroke as a newly emerging risk factor for atherosclerosis." (PMID 33628379, 2021). "On an atherogenic diet, mice deficient in PON1 develop atherosclerosis faster than control mice." (PMID 34634315, 2021). "In addition, the PON1-192R/Q human polymorphism resulted in reduced PON1 stability, lipolactonase activity and macrophage cholesterol efflux, implying a potential role of the polymorphism to atherosclerosis susceptibility." (PMID 34064071, 2021). "PON1 levels in the blood and genotype-related catalytic activity have a major impact on an individual’s susceptibility to OPs (pollutants and insecticides), development of atherosclerosis and drug metabolism." (PMID 33348669, 2020). "A statistically significant increase in the risk of more severe atherosclerosis (that is, of having the Gensini score in the higher half of the distribution) was observed for the PON1 c.575G allele carriers (odds ratio (OR) = 1.27, 95% confidence interval (CI): 1.004–1.617, p = 0.046)." (PMID 32961879, 2020). "PON1 metabolizes oxidized phospholipids and prevents oxidation of low density lipoproteins (LDLs), which is cytotoxic to endothelial cells and linked to the progression of atherosclerosis." (PMID 31234489, 2019). "Some studies suggest that decreased activity of PON1 increases the risk of development of atherosclerosis and may be considered as additional strong risk factor for CHD." (PMID 30935088, 2019). "In vivo and in vitro studies demonstrate that PON-1 protects against the damage caused by hyperhomocysteinemia associated with the development of atherosclerosis and vascular endothelial dysfunction, age-related macular degeneration, multiple sclerosis and cancer." (PMID 31052559, 2019). "It turned out that PON1 is involved in the hydrolysis of compounds that cause atherosclerosis." (PMID 31737129, 2019). "Thus, strategies to promote the increase of PON-1 activity are important to reduce the risk of development of atherosclerosis." (PMID 30660196, 2019). "A plasma concentration of 50 mM of caffeine, which is equal to the average plasma caffeine concentration of healthy individuals who consume coffee, may decrease the risk of atherosclerosis by increasing liver ApoA1 and PON1 protein levels." (PMID 29215336, 2017). "Serum PON1 activity has been inversely associated with the risk of cardiovascular disease and has been found to be decreased in several situations associated with atherosclerosis and oxidative stress." (PMID 28212288, 2017). "Previous studies aimed at elucidating the role of PON1 in the atherosclerotic process have shown that PON1-deficient mice (PON1-/-) are more susceptible to developing atherosclerosis and that mice that overexpress PON1 are less susceptible to atherosclerosis than WT mice." (PMID 28278274, 2017). "Previous studies supported a role of PON1 in atheroprotection, through its ability to prevent lipid oxidation and limit atherosclerotic lesion development; moreover, low PON1 activity has been associated with different cardiovascular pathologies, including atherosclerosis and AAA." (PMID 29099757, 2017). "Therefore, loss of PON1 enzymatic activity can promote the manifestation of atherosclerosis and CAD phenotypes." (PMID 29118461, 2017). "According to our results, caffeine may reduce atherosclerosis risk by increasing liver ApoA1 and PON1 protein levels." (PMID 29215336, 2017). "Thus, a decrease of PON1 activity caused by detoxification OPs is implicated in the pathogenesis of atherosclerosis and CVD." (PMID 26339906, 2015).
atherosclerosis (continued). "While diabetes, smoking, and obesity are established risk factors for atherosclerosis complications, several studies have suggested that PON1 may play an atheroprotective role." (PMID 26241956, 2015). "Moreover, low PON1 activity has been found in numerous pathological conditions associated with atherosclerosis, including type 1 and 2 diabetes, hypercholesterolemia and metabolic syndrome, as well as in elderly populations." (PMID 26024295, 2015). "In addition, reduced PON1 activity is an important risk factor for atherosclerosis and serum PON1 activity also predicts arterial stiffness in renal transplant recipients." (PMID 24400090, 2014). "In conclusion, although atherosclerosis is considered an inflammatory/oxidative condition, our results argue against a major role of PON1 and oxidative status in prediction of atherosclerotic risk as none of these indices impacted on the model's value in explaining the variability of CIMT." (PMID 24799979, 2014). "Human PON1 is synthesized in the liver and secreted into the blood, where it is mainly associated with HDLs, hydrolyzes oxidized phospholipids and protects against the development of atherosclerosis." (PMID 25117703, 2014). "This may provide a mechanism by which decreased PON1 activity promotes atherosclerosis and increased risk for vascular complications in type 1 diabetes." (PMID 23691522, 2013). "Several studies suggest that a low-level plasma PON-1 activity is associated with increased prevalence of atherosclerosis and could be an independent risk factor for coronary events." (PMID 23936611, 2013). "PON1 is a HDL-associated enzyme which has been demonstrated to affect atherosclerosis." (PMID 23382833, 2013). "The HDL-associated enzyme paraoxonase 1 (PON1) has anti-oxidative functions that may protect against atherosclerosis." (PMID 22615820, 2012). "In this study we observed a decrease in serum PON1 activity in insulin-resistant rats on a high-salt diet and an association among PON1, oxidative stress and inflammation, which can occur during the development of atherosclerosis." (PMID 22738670, 2012). "As macrophage apoptosis is an important feature of atherosclerotic plaque development, PON1 deficiency may lead to the enhanced atherosclerosis development observed in mice, as a result of reduced SR-BI-mediated HDL protection against apoptosis." (PMID 22824324, 2012). "PON1 has antioxidative properties, which are associated with the enzyme's capability to decrease oxidative stress in atherosclerotic lesions and to attenuate atherosclerosis development." (PMID 22548179, 2012). "Mutations in PON1 or other ROS modulating genes may result in an altered gut microbiome as an intermediate mechanism for diseases such as atherosclerosis and diabetes mellitus, and may also affect important traits such as longevity." (PMID 22952763, 2012). "In the present study, we have analyzed the influence of the PON1 Q192R polymorphism on serum lipids and inflammatory biomarkers in a cohort of 49 healthy male individuals to get a better understanding of the role of the PON1 Q192R polymorphism in the development of atherosclerosis and CHD." (PMID 21569287, 2011). "Previous studies of PON1 showed that knockout mice were highly susceptible to atherosclerosis, and serum PON1 levels, and polymorphism, were related to the level of cardiovascular disease, all of which indicate a role of PON1 for the prevention of atherosclerosis." (PMID 19922610, 2009). "Paraoxonase 1 (PON 1) as a cellular protector against oxidative damages inhibits low-density lipoprotein oxidation and plays the important roles in reducing the oxidative stress, atherosclerosis, and risk for cardiac diseases through removal of low-density lipoprotein oxidation." (PMID 35801004, 2022).
atherosclerosis (continued). "Multifaceted associations of PON1 with dyslipidaemia, ischemic cerebral stroke, and cardiovascular mortality in HD patients provide arguments for the consideration of PON1 and its protein product as therapeutic targets in the prevention of atherosclerosis and its complications in uremic patients." (PMID 33762698, 2021). "Additionally, it was observed that decreased activity of PON1 enhances the progress of atherosclerosis and may indicate the risk of atherosclerosis-related disease occurrence and severity." (PMID 33670025, 2021). "By binding to cell membranes, PON1 protects lipids against peroxidation and prevents low-density lipoprotein oxidation, which is a major cause of inflammation and is involved in the initiation of inflammatory diseases such as atherosclerosis, diabetes, and cancer." (PMID 34332593, 2021). "Hence, we conducted this meta-analysis to clarify the associations of the PON1 rs854560 polymorphism and the different plasma lipid levels by using a larger sample size and to put into consideration ethnicity and disease condition particularly atherosclerosis." (PMID 30509298, 2018). "Interestingly, both studies focused mainly on the anti-inflammatory and antioxidant properties of PON1 to explain the difference in the susceptibility to atherosclerosis of PON1-/- and PON1-Tg mice and paid little attention to the role of PON1 in the regulation of RCT." (PMID 28278274, 2017). "Reduced serum PON1 activity has been clearly established in HD patients and could contribute to accelerating the development of atherosclerosis in these patients, as they are, probably, more susceptible to the harmful effects of lipid peroxidation than healthy subjects with a normal PON1 activity." (PMID 25276769, 2014). "Named for its ability to hydrolyze organophosphates like paraoxon found in insecticides, PON1 is also able to hydrolyze N-acyl-homoserine, a lactone used by pathogenic bacteria, and lipid peroxides, thereby inhibiting the formation of foam cells known to contribute to atherosclerosis." (PMID 24222847, 2013). "Therefore, authors speculated that unfavorable lipid profile combined with lower PON-1 activity in women with endometriosis may contribute to the increased susceptibility for the development of atherosclerosis." (PMID 23861560, 2013). "Perhaps the most conclusive data were generated in the PON1-deficient mouse model and the human-PON1 transgenic mouse model, PON1 plus apolipoprotein E double-deficient mice showing increased lipoprotein oxidation and atherosclerosis than the apolipoprotein E-alone deficient mice." (PMID 22315585, 2012). "High-density lipoprotein (HDL) plays an important role in anti-atherosclerosis, with its anti-atherogenic function attributed to HDL-associated proteins such as apolipoprotein A-I (apoA-I) and paraoxonase 1 (PON1)." (PMID 41496561, 2026). "PON1 can attenuate the macrophage inflammatory response and regulate macrophage anti-atherosclerosis activities." (PMID 40377731, 2025). "High LDL oxidation has been correlated as a biomarker of atherosclerosis, and high PON1 activity has been found to lower the recurrence of symptoms in coronary heart disease." (PMID 40457011, 2025). "Extensive research underscores the positive roles of HDL and PON1 in prevention of both atherosclerosis and CVD." (PMID 40313882, 2025). "PON1 SNPs have been related to multiple inflammatory diseases, such as atherosclerosis, diabetes, and some cancer types, including lung, multiple myeloma, papillary thyroid cancer, and prostate, breast, and ovarian cancer." (PMID 40149317, 2025). "PON1 is linked to various conditions including cardiovascular disease (CVD), atherosclerosis, insulin resistance, depression, and T2DM." (PMID 40511456, 2025). "Human PON1 activity has been inversely correlated to the risk of CVD and in particular to the development of atherosclerosis." (PMID 41181110, 2025).
atherosclerosis (continued). "This study aims to systematically evaluate the impact of vigorous-intensity bodybuilding exercises on atherosclerosis biomarkers, including PON1 and ARE activities, oxLDL, LDL-C, HDL-C, TG levels, and the log(TG/HDL-C) ratio." (PMID 39459504, 2024). "In Pon1−/− mice fed with a high-fat diet, the enhancement of atherosclerosis is accompanied by the upregulation of oxidative stress, which is manifested by elevated levels of lipid peroxides in purified HDL." (PMID 39594433, 2024). "More interest should be paid to determining PON1 levels, as it is one of the best markers to be taken into consideration when assessing inflammation and the severity of atherosclerosis." (PMID 38474211, 2024). "In patients with coronary artery disease (CAD), PON1 was found to play a prominent protective role in the development of atherosclerosis, and the decrease of its activity in serum predicted the degree of coronary lesion." (PMID 38982880, 2024). "In ApoE−/− mice, Pon1 gene deletion also increased atherosclerosis and oxidative stress, manifested by elevated epitopes in plasma-oxidized phospholipid, biologically active oxidized phospholipids in isolated endogenous intermediate-density lipoprotein/LDL." (PMID 39594433, 2024). "PON3 has also been studied recently, and it has some of the proprieties of PON1, being involved in the prevention of atherosclerosis, but it only has arylesterase and lactonase activity." (PMID 38474211, 2024). "Inflammation is a major trigger of atherosclerosis, and PON-1 has been found to reduce inflammation by inhibiting the oxidation of Low-Density Lipoprotein (LDL) cholesterol." (PMID 39336967, 2024). "PON1 is known for preventing atherosclerosis through lipid-modifying properties, anti-oxidant activity, anti-inflammatory, anti-thrombosis, and anti-apoptosis effects." (PMID 39684469, 2024). "Research has shown that the genetic polymorphism in PON-1 leads to a reduction in LDL peroxidation prevention activity and the development of atherosclerosis." (PMID 39336967, 2024). "PON-1 also reduces monocyte chemotaxis and adhesion to endothelial cells, thereby preventing endothelial damage and atherosclerosis." (PMID 39336967, 2024). "One of the biggest roles of PON1 is the protection against atherosclerosis, which is given by its ability to bond with HDL and reduce LDL and triglycerides serum levels, thereby fighting against cardiovascular disease while reducing oxidative stress." (PMID 38474211, 2024). "This is relevant because PON1 has previously been related to atherosclerosis and clopidogrel bioactivation pathways." (PMID 39408985, 2024). "In mice fed with a high-fat diet, Pon1 gene deletion led to increased atherosclerosis and increased lipid peroxides levels in isolated HDL compared to Pon+/+ animals." (PMID 39594433, 2024). "Human and animal experimental studies have suggested the potential role played by PON1 in several cardiovascular and central nervous system disorders including atherosclerosis and Alzheimer's disease, respectively." (PMID 37908943, 2023). "For example, in a cohort of patients with atherosclerosis, those with the lowest PON-1 activity had a 3.4 times greater hazard of major cardiovascular events compared to those with the highest PON-1 activity." (PMID 36344783, 2023). "If a major function provided by Pon1 is to protect against atherosclerosis, potentially by breaking down oxidized lipids, it is a paradox that these diving species would lose the function of this gene." (PMID 37146172, 2023). "PON1 is noted to be a determinant of resistance to the development of atherosclerosis through hydrolysis of phospholipid and cholesteryl ester hydroperoxides." (PMID 37545608, 2023). "As long ago as 2002 a US patent was registered for the prevention of atherosclerosis by injection of a preparation of PON1 192Q isoform based on a mouse model." (PMID 36873390, 2023).